GLP1R (glucagon like peptide 1 receptor)
Diseases named in the same sentence as GLP1R in open-access papers (continued):
Sharing a sentence is not in itself a finding about the gene and the disease.
retinopathy (8 papers, 2018 to 2025). "Glucagon-like peptide-1 receptor agonists’ effect on retinopathy has been debated for the past years." (PMID 38105902, 2023). "In spite of promising results with GLP-1R agonists in preclinical studies of DR, hopes for improvements in the treatment of the condition were initially tempered by early trials that showed worsening of retinopathy in a significant number of patients." (PMID 40940761, 2025).
liver (6 papers, 2020 to 2024). "Receptors for the incretin glucagon-like peptide-1 (GLP-1R) have been found overexpressed in selected types of human tumors and may, therefore, play an increasingly important role in endocrine gastrointestinal tumor management." (PMID 31951592, 2020). "Second, the protective effects of liraglutide on liver IRI were partially reversed in GLP-1R-/- mice, indicating that liraglutide may act through non-receptor pathways." (PMID 35450076, 2022).
gastrointestinal disorders (5 papers, 2012 to 2025). "The effects of loss of GLP-1R signaling in the gastrointestinal tract including increased water content are consistent with that the most frequent adverse events following GLP-1R agonist treatments are gastrointestinal disorders including constipation." (PMID 38521185, 2024).
inflammation (5 papers, 2022 to 2026). Aberrant reaction of the microcirculation characterized by movement of fluid and leukocytes from the blood into extravascular tissues. "GLP-1R agonists can regulate OVA-induced airway inflammation and mucus secretion in mice, which are related to the inhibitory effect of GLP-1R signaling on Th2 inflammation." (PMID 36496564, 2022).
gastrointestinal disease (4 papers, 2013 to 2024). A disease that occurs in the gastrointestinal system, excluding the hepatobiliary system. "Yet, GLP-1R agonists possess multiple side effects, many of which are gastrointestinal; some documented contraindications for GLP-1R include severe renal and gastrointestinal diseases, thyroid and endocrine malignancies, and pregnancy." (PMID 38292961, 2023).
inflammatory myopathies (4 papers, 2022 to 2025). "Considering the paucity of data-based literature on GLP-1R agonism in relation to inflammatory myopathy, this review provides an overview of current evidence in the field." (PMID 38292961, 2023). "This scoping review article seeks to synthesize current findings related to GLP-1R agonism and inflammatory myopathy, with the goal of guiding future evidence-based management of IIM." (PMID 38292961, 2023). "Accordingly, GLP‐1R agonists could also be a potential therapy for the extramuscular involvement of inflammatory myopathies." (PMID 35775116, 2022). "Although large-scale clinical trials directly evaluating the impact of GLP-1R agonists on muscle function in DM1 patients are currently lacking, some basic research and reviews on other myopathies provide theoretical support for this direction." (PMID 41018201, 2025).
central nervous system diseases (3 papers, 2021 to 2023). "The theranostic of central nervous system diseases targeting GLP-1R has been gradually developed." (PMID 37780209, 2023). "GLP-1R targets may usher in a new chapter in the theranostic of central nervous system diseases." (PMID 37780209, 2023).
peripheral neuropathy (3 papers, 2013 to 2023). A disorder affecting the peripheral nervous system. "The neuroprotective activities of GLP-1R agonists following axonal injury and in peripheral neuropathies have also been documented." (PMID 33804063, 2021).
brain diseases (2 papers, 2016 to 2023). "We also show that the identified T2D-neuropathology can be counteracted by GLP-1R activation supporting recent research promoting the use of GLP-1R agonists against brain diseases." (PMID 26744321, 2016).
Hematologic Cancers (2 papers, 2024 to 2025). "For instance, the more pronounced protective effect against lymphoid and hematopoietic cancers in males compared to females suggests potential interactions between GLP-1R signaling and sex-specific physiological factors." (PMID 39796706, 2024).
GLP1R also shares sentences with these, for which no sentence is quoted: colorectal cancer (12 papers); atrial fibrillation (8); Parkinson’s (8); peripheral artery disease (8); neuropathy (7); obstructive sleep apnea (7); hyperinsulinemic hypoglycemia (6); infarction (6); renal failure (6); acute myocardial infarction (5); amyotrophic lateral sclerosis (5); bipolar disorder (5); end-stage renal disease (5); gestational diabetes (5); nicotine dependence (5); thyroid (5); Arthritis (4); binge eating disorder (4); bladder cancer (4); Cholecystitis (4); dyslipidaemia (4); endocrine diseases (4); erectile dysfunction (4); Hernia (4); hyperandrogenism (4); Hypercholesterolemia (4); left ventricular hypertrophy (4); multiple myeloma (4); alcoholic fatty liver disease (3); anorexia nervosa (3).
A further 227 diseases each share a sentence with GLP1R in 3 papers or fewer.